CRP (C-reactive protein)
Diseases named in the same sentence as CRP in open-access papers (continued):
Sharing a sentence is not in itself a finding about the gene and the disease.
Chlamydia pneumonia (3 papers, 2006 to 2016). "They studied the joint effect of chronic Chlamydia pneumoniae (CP) infection, persistently elevated human heat-shock protein 60 (h-hsp60) antibodies and C-reactive protein (CRP) on coronary risk." (PMID 16608530, 2006). "We measured high sensitivity C-reactive protein (hs-CRP), procalcitonin, E-selectin, intercellular adhesion molecule-1 (ICAM-1), serum level of immune complexes (IC), and identified antibodies against Herpes simplex virus type 1 (HSV), Cytomegalovirus, Chlamydia pneumonia, and Helicobacter pylori." (PMID 28051279, 2016).
chordoma (3 papers, 2016 to 2023). Chordomas are rare malignant tumors arising from embryonic remnants of the notochord in axial skeleton. "A multicentered approach involving CRP and other biomarkers to be tested in settings with combined treatment including surgery and other upcoming treatment options, i.e., carbon ions based on individual risk of patients could be the next step to find new treatment algorithms for chordoma." (PMID 27091202, 2016). "Pre-operative CRP levels appear to be a biomarker for disease-specific survival in patients with chordoma of the lumbar spine and sacrum." (PMID 27091202, 2016). "Survival rates of 24 patients (18 males, 6 females) (mean age 67 years (SD ± 16; range 20–85 years); minimum follow-up 2 years, mean follow-up 5 years (SD ± 5; range 2–19 years)) with chordoma of the lower spine and sacrum were assessed with a focus on pre-operative CRP levels." (PMID 27091202, 2016). "To conclude, this finding of pre-operative CRP levels as a prognostic marker in disease-specific survival for patients with chordoma may be an important aspect for individualized treatment in this disease that is characterized by high recurrence and morbidity." (PMID 27091202, 2016). "This may explain that local expansion in chordoma and any other kinds of tumor leads to higher CRP levels in more aggressive tumors by mechanical forces." (PMID 27091202, 2016). "Even minor CRP elevations show a trend towards low survival in this cohort of chordoma patients." (PMID 27091202, 2016). "In addition, preoperative C-reactive protein and pretreatment GPS were not collected due to the not routine measurement in examinations; and their associations with SIS were not analyzed in this study, while the previous study showed the prognostic value of C-reactive protein in chordoma." (PMID 36313652, 2022). "The impact on survival of pre-operative serum CRP levels in patients with chordoma has not yet been elucidated." (PMID 27091202, 2016).
chronic lymphocytic leukemia (3 papers, 2019 to 2024). "This gene is involved with hexose transport in brain, spleen and leukocytes, as well as increasingly expressed in chronic lymphocytic leukemia, but a PubMed search reveals no apparent relevance to clinical inflammation or CRP expression." (PMID 31622379, 2019).
clostridium difficile infection (3 papers, 2021 to 2022). Symptomatic infection due to the spore-forming bacterium clostridium difficile. "Increased Phascolarctobacterium is associated with benefits that include protection from Clostridium difficile infection and lower levels of C-reactive protein (CRP)." (PMID 35475626, 2022). "Initial elevation of CRP levels may be partly due to erysipelas, and the second spike Clostridium difficile infection and the progression of lung damage." (PMID 36550575, 2022). "The patients with Clostridium difficile-associated diarrhea had significantly elevated mean platelet volume, neutrophil–lymphocyte ratio, and serum C-reactive protein levels compared with age- and sex-matched subjects with diarrhea but without Clostridium difficile infection." (PMID 33407626, 2021).
colon adenoma (3 papers, 2017 to 2021). An adenoma that arises from the colon. "In a 3×2 randomized trial of aspirin (81 or 325 mg, placebo) and folic acid (1 mg, placebo) to prevent recurrence of colonic adenoma, it was found that higher dose aspirin (325 mg) reduced serum C reactive protein, but this was abrogated by folic acid." (PMID 34866142, 2021).
colonic disease (3 papers, 2015 to 2025). "In addition, shorter disease duration, isolated colonic disease, elevated CRP, the absence of previous surgery in CD and a hemoglobin >11.5 mg/dL in UC are considered to have predictive value." (PMID 31126015, 2019).
colonic diverticulitis (3 papers, 2017 to 2023). "Laboratory values—WBC (p = 0.008) and neutrophil (p = 0.003) counts, MDW (p < 0.001), and CRP level (p < 0.001)—were significantly higher in the complicated colonic diverticulitis group." (PMID 36977993, 2023). "The secondary aim was to examine the diagnostic accuracy of temperature, CRP, and white blood cell (WBC) count alone in the diagnosis of acute colonic diverticulitis in patients admitted with acute abdominal pain." (PMID 27613727, 2017). "ROC curve analysis to assess CRP in the diagnostics of acute colonic diverticulitis has previously been reported with an AUC ranging from 0.72 to 0.94, which is comparable to the present results." (PMID 27613727, 2017). "We investigated various markers such as NLR, LMR, PLR, CRP/albumin ratio, and mGPS to evaluate risk factors for the failure of non-operative treatment of colonic diverticulitis." (PMID 36927780, 2023). "Furthermore, the analyses proved CRP to be a valuable initial laboratory test in the differentiation of acute colonic diverticulitis from other acute abdominal conditions." (PMID 27613727, 2017). "From the results of the study, it was concluded that the increase in age, WBC count, neutrophil count, CRP level, NLR, PLR, and MDW were related to the severity of colonic diverticulitis." (PMID 36977993, 2023). "This study confirms that a clinical diagnosis of acute colonic diverticulitis is achievable by non-specialist doctors at the emergency department and applies specifically to patients younger than 65 years with localized tenderness in the left lower quadrant and an elevated CRP." (PMID 27613727, 2017).
colorectal polyps (3 papers, 2021 to 2023). "In this study, we first discussed the significance of the PLR and CRP levels in their ability to predict the histopathological type of colorectal polyps." (PMID 34001040, 2021). "This study is first to investigate the relationship between inflammatory factors (PLR and CRP) and histopathological type in patients with colorectal polyps." (PMID 34001040, 2021). "The platelet-to-lymphocyte ratio (PLR) and C-reactive protein (CRP) level are markers that have been reported to predict the histological type of various tumors, and here, we evaluated their utility in predicting colorectal polyp histological types." (PMID 34001040, 2021). "Further studies are needed to understand the role of the PLR and CRP alone or in combination with other inflammatory biomarkers in predicting the histopathological type of colorectal polyps." (PMID 34001040, 2021). "We found that both the PLR and CRP are novel preoperative biomarkers that are closely related to the histopathological type of colorectal polyps." (PMID 34001040, 2021). "In our study, the PLR and CRP were shown to be economical, reliable, and convenient tools for predicting the histopathological type of colorectal polyps." (PMID 34001040, 2021). "In our study, the PLR and CRP were shown to be economical, reliable, and convenient tools for predicting the pathological type of colorectal polyps." (PMID 34001040, 2021). "We found that both the PLR and CRP are novel preoperative biomarkers that are closely related to the histopathological types of colorectal polyps." (PMID 34001040, 2021). "Preoperative PLR and CRP are correlated with the colorectal polyp histological type." (PMID 34001040, 2021). "However, to our knowledge, no studies have reported the association among PLR, CRP, and the histological type of colorectal polyps." (PMID 34001040, 2021). "However, few articles mention PLR and CRP as predictors of colorectal polyps." (PMID 34001040, 2021). "Therefore, this study was designed to assess the relationships among PLR, CRP and colorectal polyp histological type and to identify simple and practical inflammation-related variables and clinicopathological factors that can be used to predict the histological type of colorectal polyps." (PMID 34001040, 2021). "However, to our knowledge, no studies have reported the association among PLR, CRP and histological type of colorectal polyps." (PMID 34001040, 2021). "Patients with colorectal polyps were then separated into a high PLR group (> 113.32) and a low PLR group (< 113.32) as well as a high CRP group (> 0.39) and a low CRP group (< 0.39)." (PMID 34001040, 2021). "Since no study has assessed the correlation between the PLR or CRP level and the histopathological type of colorectal polyps, ROC curves were used to determine the cut-off values." (PMID 34001040, 2021). "To date, no study has reported the relationships among PLR, CRP and the histopathological types of colorectal polyps." (PMID 34001040, 2021).
Constipation (3 papers, 2022 to 2025). Infrequent or difficult evacuation of feces. "Clinical trials with Lactobacillus rhamnosus JYLR-127 demonstrate significant improvements in post-surgical constipation, with defecation frequency increasing from 2.06 to 3.04 times/week and a concurrent reduction in inflammatory markers (CRP decreased from 24.45 to 15.42 mg/L)." (PMID 41367416, 2025). "Thirdly, emerging evidence from experimental research showed that short sleep duration might enhance vulnerability to constipation by altering average levels of inflammatory markers such as interleukin-6 and C-reactive protein." (PMID 36034289, 2022).
cutaneous melanoma (3 papers, 2014 to 2021). A primary melanoma arising from atypical melanocytes in the skin. "For skin melanoma, somatic mutations in four genes were significantly enriched in their protein pocket regions, including CRP (P = 2.2 × 10-6), NCF1 (P = 6.3 × 10-4), EPO (P = 2.2 × 10-3), and RWDD1 (P = 2.2 × 10-3)." (PMID 25360158, 2014). "In the univariate analyses, CRP level, M1a disease, and cutaneous melanoma diagnosis potentially confounded the estimate." (PMID 34771712, 2021). "These showed that having a high LDH level, CRP level, cutaneous melanoma, M1a, or M1d status potentially confounded the result." (PMID 34771712, 2021). "Univariate Cox analyses were made regarding LDH level higher versus lower than ULN, CRP level higher versus lower than 2x ULN, cutaneous melanoma versus other diagnoses, M1a versus M1b–d, and M1d versus M1a–c disease." (PMID 34771712, 2021).
diarrheal disease (3 papers, 2015 to 2024). The condition of having at least three loose or liquid bowel movements each day. "Tanzanian children infected with Giardia were shown to have reduced incidence of diarrheal disease and fever, and lower serum C-reactive protein levels." (PMID 26569316, 2015). "It is worth noting that in pigs experimentally infected with ETEC, supplementary tryptophan did not have any effect on CRP-level after infection, diarrheal disease, or ETEC shedding, but increased serum serotonin levels, which in turn increased post-weaning performance." (PMID 38430452, 2024).
differentiated thyroid carcinoma (3 papers, 2023 to 2026). Differentiated thyroid carcinoma (DTC), also known as papillary or follicular thyroid carcinoma, is a slow-growing malignancy usually presenting in adults as an asymptomatic thyroid mass. "Additionally, a study found that higher preoperative CRP values have a robust prognostic impact on recurrence-free survival in differentiated thyroid carcinoma cases, and higher preoperative CRP levels were linked to age ≥ 55 years and T3 + T4." (PMID 37873776, 2023). "Increased hsCRP has been reported as a marker in Papillary Thyroid Carcinoma (PTC), but other data have demonstrated that CRP may not a have significant increase nor importance in chronic PTC." (PMID 37873776, 2023).
dissection (3 papers, 2013 to 2022). The separation and isolation of tissues for surgical purposes, or for the analysis or study of their structures. "In this regard, a negative procalcitonin test with a high C-reactive protein level is a new and good diagnostic marker of aortic dissection, especially the painless type." (PMID 23843799, 2013).
Dysmenorrhea (3 papers, 2022 to 2024). Pain during menstruation that interferes with daily activities. "Based on the obtained linear model, it is expected that the CRP concentration will increase, both after manual therapy and ibuprofen administration, in young women with dysmenorrhea." (PMID 35628817, 2022). "Based on the known literature, it seems that our study is the first to evaluate the impact of manual therapy on progesterone, estradiol and CRP levels in young women with dysmenorrhea." (PMID 35628817, 2022). "Another study on female with dysmenorrhea found that OEA supplement reduced malondialdehyde (MDA), c-reactive protein (CRP), and TNF-α significantly." (PMID 38778429, 2024). "Among women with dysmenorrhea in group A after manual therapy, we found a strong negative correlation between mean 17-β estradiol and CRP levels (p = 0.002; ρ = −0.659)." (PMID 35628817, 2022).
eating disorder (3 papers, 2020 to 2025). A broad group of psychological disorders with abnormal eating behaviors leading to physiological effects from overeating or insufficient food intake. "The aim of this study is to investigate whether serum levels of IL-6 and CRP at age nine years are associated with eating disorder diagnoses, disordered eating behaviours and cognitions during adolescence using a large UK general population prospective birth cohort." (PMID 32755646, 2020). "Following stepwise regression analysis to quantify associations between covariates and SA status, the mediation effects of eating disorders and CRP were examined." (PMID 40791098, 2025). "We investigated the association between serum-levels of interleukin 6 (IL-6) and C-reactive protein (CRP) measured in childhood and eating disorders and related behaviours and cognitions in adolescence in a large general population sample." (PMID 32755646, 2020). "Our exposures were thirds of IL6 and CRP derived from serum measurements taken at age nine years, and outcomes were eating disorder diagnoses and self-reported disordered eating behaviours at ages 14, 16, and 18 years." (PMID 32755646, 2020). "There was little evidence of an association between CRP and IL-6 and adolescent eating disorder outcomes." (PMID 32755646, 2020).
encephalomyelitis (3 papers, 2021 to 2025). Inflammation of the brain and the spinal cord. "In the case of encephalomyelitis, it has been shown that CRP was protective by suppressing both Th1 response directly and Th17 response indirectly." (PMID 38650931, 2024). "Brain damage marker S-100B and C reactive protein increased before symptoms or signs of encephalomyelitis and peaked when the patient fell into a coma." (PMID 34215689, 2021).
endometrioid carcinoma (3 papers, 2019 to 2023). "In analyses examining histotypes and low malignant potential tumours, there was suggestive evidence for an inverse association of CRP with endometrioid carcinoma (OR 0.90, 95% CI 0.82–1.00; P = 0.049)." (PMID 31390370, 2019). "Our MR analyses found some evidence for an unexpected inverse association of CRP, a marker of systemic inflammation, with endometrioid carcinoma." (PMID 31390370, 2019).
endometrioid tumor (3 papers, 2020 to 2022). A benign, borderline, or malignant epithelial tumor of the female reproductive system characterized by the presence of glands and/or cysts lined by neoplastic cells that resemble endometrial cells. "A small study of 176 women with type 1 endometrial cancer found high pre-operative CRP levels were associated with increased all-cause mortality but the authors failed to include non-endometrioid tumors in their analysis or adjust for important confounders." (PMID 34802721, 2022).
experimental autoimmune encephalomyelitis (3 papers, 2015 to 2023). An autoimmune demyelinating disease of the central nervous system that is produced experimentally in animals by the injection of homogenized brain or spinal cord in Freund's adjuvant. "For example, we have shown that human CRP inhibits the progression of experimental autoimmune encephalomyelitis (EAE) in CRP transgenic mice by shifting CD4+ T cells away from the TH1 and toward the TH2 subset." (PMID 29556231, 2018). "Our laboratory has used transgenic mice expressing human CRP in the liver (CRPtg) to demonstrate that blood-borne human CRP ameliorates experimental autoimmune encephalomyelitis (EAE), a rodent model of MS." (PMID 26421184, 2015). "Previously, we have shown that human CRP transgenic mice (CRPtg) are resistant to experimental autoimmune encephalomyelitis (EAE), a disease comparable to human multiple sclerosis (MS) i.e., they have delayed onset of disease and milder clinical symptoms compared to wild type (WT) mice." (PMID 29556231, 2018). "Experimental autoimmune encephalomyelitis (EAE) outcomes in C-reactive protein transgenic mice (CRPtg) lacking mouse FcγRIIB and/or expressing human FcγRIIB." (PMID 29556231, 2018). "Moreover, an in vitro study demonstrated that human CRP directly contributes to adaptive immunity, with its native form specifically binding to human Jurkat T cells and to mouse naive CD4+ T cells, modulating their Th1 and Th2 responses and thus alleviating experimental autoimmune encephalomyelitis." (PMID 37873776, 2023).
food allergy (3 papers, 2019 to 2025). Gastrointestinal disturbances, skin eruptions, or shock due to allergic reactions to allergens in food. "In early childhood, a deficient vitamin D status correlated with the presence of food allergy, while higher plasma levels of vitamin D correlated to lower levels of C-reactive protein (CRP), IL-6 and TNF-α, indicating a lower degree of inflammation." (PMID 33801051, 2021).
Gastrointestinal inflammation (3 papers, 2012 to 2025). Inflammation of the alimentary part of the gastrointestinal system. "Dogs with gastrointestinal inflammation showed significantly higher serum CRP and fecal calprotectin concentrations compared to healthy controls." (PMID 40979161, 2025). "Even though they may be superior to CRP or ESR with higher sensitivity and specificity in detecting gastrointestinal inflammation, they are not specific markers for IBD; and they are inconvenient and unpleasant for stool sampling." (PMID 23058104, 2012).
glucose metabolism disorders (3 papers, 2017 to 2023). "Elevated concentrations of CRP, IL-6, and TNF with suboptimal VD levels have been associated with an increased risk of cardiovascular events, glucose metabolism disorders, neurodegenerative diseases, and overall mortality." (PMID 37175418, 2023). "The relationship between elevated serum hs-CRP level and glucose metabolism disorders may be intermediated by increased secretion of TNF-α and IL-6." (PMID 28361994, 2017).
goiter (3 papers, 2016 to 2024). Enlargement of the thyroid gland usually caused by lack of iodine in the diet, hyperthyroidism, or thyroid nodules. "Recurrence in patients treated with prednisolone was defined as the presence of symptoms such as tenderness, painful goiter, and CRP elevation." (PMID 39213615, 2024). "FNA features, painful goiter, and elevated erythrocyte sedimentation rate and C-reactive protein established the definitive diagnosis." (PMID 29686830, 2018).
herpangina (3 papers, 2014 to 2024). "In this study, we found CA4 usually caused herpangina with high grade fever, leukocytosis and higher CRP but rarely caused complications." (PMID 24504149, 2014).
hip osteoarthritis (3 papers, 2020 to 2025). "Neopterin may provide more reliable information regarding inflammatory status of a patient by being more sensitive than CRP or IL-6, which have not been able to distinguish between knee and hip osteoarthritis or subsequent arthroplasty surgery." (PMID 34403444, 2021).